SLC35F3 (solute carrier family 35 member F3)
Description:
Mediates thiamine transport. Also mediates choline transport, although the underlying transport mechanism remains to be elucidated.
Synonyms: FLJ37712
Tractability: Antibody: UniProt predicts a signal peptide or a membrane-spanning region.
Gene: Protein-coding gene on chromosome 1 (233,904,676 to 234,324,511, forward strand). Ensembl gene ENSG00000183780.
Subcellular location: Membrane
Subcellular location (Human Protein Atlas): Golgi apparatus; Nucleoli
Gene Ontology:
Molecular function: choline transmembrane transporter activity
Biological process: choline transport; thiamine transport
Cellular component: membrane
Genetic constraint (gnomAD): Loss-of-function variants: 24 observed, 48.44 expected, observed/expected ratio (o/e) 0.5, 90% interval 0.36 to 0.7. The upper end of that interval is the gene's LOEUF score, 0.7, which puts it in group 2 of 6, group 1 being the genes least tolerant of losing a copy. Missense variants: 516 observed, 651.95 expected, observed/expected ratio (o/e) 0.79, 90% interval 0.74 to 0.85. Synonymous variants: 274 observed, 274.69 expected, observed/expected ratio (o/e) 1, 90% interval 0.9 to 1.1.
Homologues: Orthologues: chimpanzee SLC35F3 (99% identical), macaque SLC35F3 (99% identical), dog SLC35F3 (95% identical), pig SLC35F3 (94% identical), rat Slc35f3 (92% identical), guinea pig SLC35F3 (76% identical), mouse Slc35f3 (76% identical), rabbit SLC35F3 (76% identical), tropical clawed frog slc35f3 (65% identical), zebrafish slc35f3b (58% identical), zebrafish slc35f3a (48% identical), Drosophila melanogaster CG42322 (27% identical), and 1 more. Paralogues in human: SLC35F4 (47% identical).
Diseases named in the same sentence as SLC35F3 in open-access papers:
SLC35F3 is named in the same sentence as 13 diseases in open-access papers, as found by Europe PMC text mining. Sharing a sentence is not in itself a finding about the gene and the disease. The quoted sentences say what the papers report.
Hypertension (8 papers, 2016 to 2025). The presence of chronic increased pressure in the systemic arterial system. "Studies in humans have linked SLC35F3 variants to hypertension and thiamine supplementation has shown positive effects on reducing high blood pressure." (PMID 40826322, 2025). "SLC35F3 was identified as a thiamine transporter, and a variant in the gene (rs17514104) was linked with the risk for hypertension and erythrocyte thiamine content." (PMID 39098524, 2024). "SLC35F3, a gene associated with the nervous system, has been linked to hypertension and bipolar disorder." (PMID 38584840, 2024). "In Chinese patients with hypertension, the CG and GG genotypes of SLC35F3 rs34032258 were associated with elevated diastolic blood pressure levels." (PMID 36678339, 2023). "SLC35F3 has been linked to hypertension risk and protein-caloric malnutrition, thereby reflecting the coenzyme function of thiamine in carbohydrate metabolism." (PMID 36678339, 2023). "A recent study suggested that SLC35F3 which encoded a thiamine transporter was a new candidate gene for hypertension." (PMID 27379158, 2016). "We found eight genetic variants in the coding regions of SLC35F3 and subsequently genotyped a non-synonymous variant rs34032258 (C > G) in 1060 hypertension patients and 1467 controls." (PMID 27379158, 2016). "In summary, this study is the first to report the association between a missense variant, rs34032258, in the SLC35F3 gene and hypertension in a Chinese Han population." (PMID 27379158, 2016). "The goal of this study was to investigate the association between the single-nucleotide polymorphisms (SNPs) in the SLC35F3 gene and hypertension in a Chinese population." (PMID 27379158, 2016). "Additionally, SLC35F3, a newly identified thiamine transporter, has been linked to plasma thiamine levels and hypertension." (PMID 40444179, 2025). "Mutations in SLC35F3 gene may reduce transport efficiency, highlighting its potential as a therapeutic target for conditions like hypertension." (PMID 40444179, 2025). "The SLC35F3 gene, a diabetes-specific biomarker, is a thiamine transporter that exhibits polymorphisms related to increased blood pressure and potential higher risk of hypertension." (PMID 36870961, 2023). "Hypertension, a risk factor for MetS, has been linked with SLC35F3." (PMID 36678339, 2023). "In conclusion, we found that the rs34032258 in the SLC35F3 gene was associated with high blood pressure and may increase the risk of hypertension." (PMID 27379158, 2016). "In this study, we explored whether variants in the coding regions of the SLC35F3 gene contributed to blood pressure variation and hypertension." (PMID 27379158, 2016). "The genetic study highlighted the role of the SLC35F3 gene in thiamine transport and its relationship with hypertension." (PMID 40243711, 2025). "By employing a genomic approach, subjects with extreme blood pressure values have been examined, underscoring the significance of SLC35F3 in multiple clinical, genetic, and biochemical contexts related to hypertension." (PMID 40243711, 2025). "Several studies have reported a link between carbohydrates and MetS, or between SLC35F3 and MetS components such as hypertension." (PMID 36678339, 2023). "By indicating a role in thiamine transport, these results show that genetic variations in SLC35F3 can predict not just hypertension but also several cardiovascular and autonomic disorders." (PMID 40243711, 2025).
metabolic syndrome (3 papers, 2023 to 2024). A cluster of metabolic risk factors for CARDIOVASCULAR DISEASES and TYPE 2 DIABETES MELLITUS. "This study aimed to investigate the impact of the interaction between SLC35F3 and dietary carbohydrate intake on the incidence of metabolic syndrome (MetS)." (PMID 36678339, 2023). "A 1.1 kb deletion on chromosome 1 (dbVar ID: nssv15849193, 1:234318630–234,319,762) that disrupts the thiamine transporter SLC35F3 (Solute Carrier Family 35 Member F3) was associated with higher LDL cholesterol in childhood, suggesting the link between thiamine deficiency and dyslipidemia." (PMID 38110883, 2023). "The interaction between SLC35F3 and dietary carbohydrate intake has a significant impact on the incidence rate of metabolic syndrome (MetS)." (PMID 39414367, 2024).
Thiamine deficiency (2 papers, 2023). Thiamine deficiency is a condition that occurs due to not enough thiamine (vitamin B1). "In subjects with the rs17514104 TT genotype of SLC35F3, erythrocyte thiamine content was decreased, and hereditary cardiovascular characteristics associated with thiamine deficiency were predicted." (PMID 36678339, 2023). "In a previous study, the SLC35F3 risk allele was found to be associated with inherited cardiovascular traits related to thiamine deficiency." (PMID 36678339, 2023). "In summary, a high-carbohydrate diet and SLC35F3 genetic variants induced thiamin deficiency, which may lead to the incidence of MetS." (PMID 36678339, 2023).
COVID-19 (1 paper, 2025). A disease caused by infection with severe acute respiratory syndrome coronavirus 2. "By 6 weeks post-inclusion (T2), COVID-19 hypermethylation of genes with lowest p-value included NXN, FMNL2, ZBTB46, SLC35F3, and SHQ1, and the hypomethylated genes included ELMO1, XBP1, GRIK1, TNFAIP8, and SH3BP5." (PMID 41227320, 2025).
diabetes (1 paper, 2023). "We also found diabetes-specific biomarkers as SLC35F3 gene, which was exclusively hypermethylated in the ObDia group." (PMID 36870961, 2023).
lung adenocarcinoma (1 paper, 2024). A carcinoma that arises from the lung and is characterized by the presence of malignant glandular epithelial cells. "The role of solute carrier family 35 member F3 (SLC35F3) in lung adenocarcinoma (LUAD) remains unclear." (PMID 39414367, 2024).
tumor (4 papers, 2023 to 2024). "The research explored the potential regulatory mechanisms associated with SLC35F3, including its interactions with immune infiltration, tumor mutational burden (TMB), and drug sensitivity in LUAD." (PMID 39414367, 2024). "The research also explored potential regulatory mechanisms of SLC35F3, including its interactions with immune infiltration, tumor mutational burden (TMB), and drug sensitivity in LUAD." (PMID 39414367, 2024). "Consequently, it can be concluded that aberrant expression of SLC35F3 is associated with tumor development." (PMID 39414367, 2024). "TENM4 and ACSM3, as well as CADPS and SLC35F3, were highly expressed in clusters 5 and 13, respectively, which represented two different sub-clusters in the tumor–stroma interface area." (PMID 38473208, 2024). "The exact nature of the connection between SLC35F3 and the tumor microenvironment (TME) is still ambiguous." (PMID 39414367, 2024). "The hot genes with the most positive signal events in the normal-specific group were RBPJ, PFKFB3, CAMK1D, ACACB, and WWOX, whereas the hot genes in the tumor-specific group were SLC35F3, PCDH7, NF1, and RAB27B." (PMID 36895481, 2023).
cancer (1 paper, 2024). A tumor composed of atypical neoplastic, often pleomorphic cells that invade other tissues. "This study aimed to analyze the expression levels of SLC35F3 in different cancer types, particularly focusing on LUAD, by utilizing data from the Cancer Genome Atlas (TCGA) database to evaluate its potential diagnostic significance." (PMID 39414367, 2024). "Whether SLC35F3 can be a marker for multiple types of cancer will depend on a joint study by multiple teams, and we may conduct this joint study in the future." (PMID 39414367, 2024). "The aberrant expression of SLC35F3 was observed in both pan‐cancer and LUAD." (PMID 39414367, 2024). "This study aimed to examine the expression patterns of SLC35F3 in various cancer types, particularly focusing on LUAD, by analyzing data from the Cancer Genome Atlas (TCGA) database to evaluate its clinical relevance." (PMID 39414367, 2024).
SLC35F3 also shares sentences with these, for which no sentence is quoted: bipolar disorder (1 paper); glioma (1); protein-calorie malnutrition (1); schizophrenia (1); systemic lupus erythematosus (1).